RPN2 (ribophorin II)
Diseases named in the same sentence as RPN2 in open-access papers (continued):
Sharing a sentence is not in itself a finding about the gene and the disease.
tumor (continued). "Furthermore, we investigated whether RPN2 could regulate EGFR glycosylation in xenograft tumor tissues, and immunofluorescence staining showed that EGFR localization was altered and protein expression decreased by RPN2 silencing." (PMID 29069815, 2017). "In addition, Ki67 staining was performed to investigate the proliferation activity of tumor tissue with RPN2 or EGFR silencing, and our results revealed that the expression level of Ki67 was higher in control mice than in mice inoculated with HCT116-shRPN2 and HCT116-shEGFR." (PMID 29069815, 2017). "In addition, RPN2 staining was also strongly associated with distant metastasis (p = 0.0007) and histological differentiation (p = 0.015), but not with gender, age or tumor location." (PMID 26388988, 2015). "Furthermore, a novel function of RPN2-mediated tumor cell malignancy was recently reported." (PMID 25181275, 2014). "Silencing of RPN2 also inhibited the expression of HK-2, PDK1, and LDHA in these cells and decreased LDHA level in mouse tumor tissues." (PMID 35156537, 2022). "In a recent study, RPN2 was reported to be modulated by circNFIX, and promoted GBM tumor growth in vivo and in vitro." (PMID 32404045, 2020). "RPN2 silencing resulted in reduced CD63 glycosylation and deregulated localization in tumor cells, which regulates drug resistance and tumor cell invasion." (PMID 25181275, 2014). "We then compared RPN2 expression levels in tumor samples from these 34 patients, with or without GBM recurrence." (PMID 32404045, 2020). "After subcutaneous tumor formation for approximately 3 weeks for all groups, TMZ (30 mg kg/day/per mouse) and DMSO (0.3%) treatment every 3 days were further performed to treat one of the two groups (sh-NC and sh-RPN2 group), respectively." (PMID 33087705, 2020). "Here we show that administration of ABT-737 can overcome the radioresistance in RPN2 overexpressed GBM cells, suggesting that inhibition of MCL1 could be a therapy strategy for GBM patients with abnormal tumor RPN2 expression." (PMID 32404045, 2020). "Subcutaneous tumor development of RPN2 or EGFR shRNA-mediated stable knockdown or negative control of HCT116 cells were monitored by measuring the tumor size and weight every 4 days." (PMID 29069815, 2017). "The results revealed that RPN2 expression level was strongly correlated with several variables including stages (P=0.044), differentiation (P=0.007) and tumor size (P=0.009, mean=40mm), but not with gender, age, tumor location or metastasis." (PMID 29069815, 2017).
infection (4 papers, 2014 to 2023). The state of being infected such as from the introduction of a foreign agent such as serum, vaccine, antigenic substance or organism. "We then found that RNAi targeting each of four other OST complex components, ribo-1/ribophorin I, stt-3/STT3, ostb-1/OST48 and ostd-1/ribophorin II, substantially reduced worm survival under PA14 infection." (PMID 32130226, 2020).
RPN2 also shares sentences with these, for which no sentence is quoted: non-small cell lung carcinoma (7 papers); nasopharyngeal carcinoma (4); laryngeal squamous cell carcinoma (3); breast tumor (2); ovarian carcinoma (2); adenocarcinoma (1); COVID-19 (1); gastric adenocarcinoma (1); lung squamous cell carcinoma (1); oral cancer (1); sarcoma (1); small cell lung carcinoma (1); soft tissue sarcoma (1); squamous cell carcinoma (1).